CDK5 (cyclin dependent kinase 5)
Diseases named in the same sentence as CDK5 in open-access papers (continued):
Sharing a sentence is not in itself a finding about the gene and the disease.
breast carcinoma (continued). "TGFβ1 treatment in breast cancer cells triggers active CDK5/p35 to phosphorylate Focal Adhesion Kinase (FAK) at S732, causing metastatic invasion and EMT by potentiating F-actin bundle formation." (PMID 37993880, 2023). "CDK5 function has also been found to be generally prosurvival in a number of different cancers, including breast cancer and medulloblastoma." (PMID 37377891, 2023). "There is much evidence showing the role of CDK5 in the migration of numerous cancers, including pancreatic cancer, breast cancer, lung cancer, liver cancer, glioblastoma, prostate cancer, and pituitary cancer." (PMID 33396266, 2020). "High expression of CDK5 correlates with poor prognosis and shorter patient survival in non-small cell lung, small cell lung, ovarian, colorectal and breast cancers, as well as in multiple myeloma." (PMID 31910742, 2020). "As with breast cancer cells depleted of Cdk5 by siRNA, we determined here that Cdk5−/− MEFs exhibit increased mPTP opening that is reversed by the mPTP desensitizers, CsA and SFA, and show increased [Ca2+]mt level that induces mPTP opening." (PMID 32024968, 2020). "To do this, we used, in addition to the prostate cancer cell line PC3, the hepatoma cell line HepG2 and the breast cancer cell line MDA-MB 231 in which we eliminated CDK5 by using the CRISPR-Cas9 technique." (PMID 31013770, 2019). "One study demonstrated that CDK5 promotes DNA replication due to stress checkpoints, and therefore contributes to the metastasis of breast cancer." (PMID 31395805, 2019). "CDK5 has been reported to participate in growth and metastasis of several tumors, such as breast cancer, gastric cancer, lung cancer, liver cancer, pancreatic cancer, prostate cancer, medullary thyroid carcinoma, and myeloma." (PMID 31272499, 2019). "This is in agreement with what has been reported for other kinds of cancer, for example, breast cancer, where the Cdk5-FAK pathway downstream of TGF-β signaling is necessary for EMT." (PMID 31614664, 2019). "Elevated CDK5 and its kinase activity have been reported in different types of cancers including breast cancer, lung cancer, liver cancer, pancreatic cancer, thyroid carcinoma, and myeloma." (PMID 31272499, 2019). "Depletion of Cdk5 by short-hairpin RNA (shRNA) in breast cancer cells MDA-MB-231 significantly diminished ADD1 T724 phosphorylation." (PMID 31548578, 2019). "TMX, which is the most prescribed hormone therapy for breast cancer, is a new CDK5/p25 interaction blocker and suppresses CDK5 activity eventually." (PMID 31272499, 2019). "Increasing researches have revealed that the abnormal expression of CDK5 participated in the tumor progression and metastasis across various solid malignancies, including breast cancer, lung cancer, prostate cancer, and liver cancer." (PMID 31311512, 2019). "The increased lamellipodia formation and cell migration of human breast cancer cells MDA-MB-231 by EGF were accompanied by Cdk5 activation and increased phosphorylation of ADD1 at T724." (PMID 31548578, 2019). "To investigate the epigenetic events that were involved in the activation of CDK5 in breast cancer, we first examined the histone methylation status using ChIP assays." (PMID 29325547, 2018). "Cdk5 is essential for TGFβ1-induced EMT and breast cancer progression, further linking Cdk5 to aggressiveness and EMT." (PMID 30452490, 2018). "For example, FIBP can bind to KIAA0528 and CDK5 to form a stable complex, which participates in breast cancer cell growth and migration." (PMID 30275459, 2018). "Our work also shows Cdk5 and p35 are significantly increased in clinical breast cancer tissues and in breast cancer cell lines exposed to paclitaxel at transcriptional and translational levels." (PMID 28288624, 2017). "In breast cancer, CDK5 takes part in epithelial-mesenchymal transition induced by TGF-β1which is vital for tumor metastasis." (PMID 26860827, 2016).
breast carcinoma (continued). "CDK5 was reported to be involved in the regulation of proliferation and survival of breast cancer cells, and CDK5 was characterized as a downstream target of extracellular regulated protein kinases in carboplatin-induced cell death." (PMID 27406233, 2016). "CDK5 has been reported to be upregulated in prostate cancer, breast cancer, medullary thyroid carcinoma, pituitary adenoma, and hepatocellular carcinoma, and CDK5 gene amplification was found in lung cancer." (PMID 26860827, 2016). "Overexpression of CDK5 in breast cancer has been found to correlate with several poor prognostic parameters." (PMID 27557521, 2016). "Actually, elevated CDK5 expression has been detected in different classes of cancers, such as lung, pancreatic, neuroendocrine thyroid, and breast cancer." (PMID 26205145, 2015). "Consistent with our study, CDK5 expression was observed to be overexpressed in NSCLC and breast cancer, which implies that CDK5 serves as an important role in the tumorigenesis of different malignancies." (PMID 26205145, 2015). "TGFβ has been reported to induce CDK5 and p35 expression in breast cancer cells." (PMID 37377891, 2023). "Similar to breast cancer cells, prostate cancer cells express high levels of CDK5 and p35." (PMID 37993880, 2023). "CDK5 also promotes chemotaxis in breast cancer cells by phosphorylating Talin’s head domain." (PMID 37993880, 2023). "For example, studies have demonstrated that suppressing CDK5 can impede cell motility and tumor development in the mesenchymal breast cancer cell lines MDA-MB-231 and BT549, while elevated expression of PRKDC promotes breast cancer cell proliferation by regulating p38 MAPK signaling." (PMID 38091511, 2022). "In breast cancer, EGF (epidermal growth factor) stimulation activates CDK5 to phosphorylate Girdin (Gα-interacting vesicle associated protein) at Ser1674, which activates the downstream G-coupled receptor-dependent signaling pathway for promoting cell migration." (PMID 35006426, 2021). "In addition, small molecules like PHA-767491 and PHA793887 were reported to inhibit the activity of CDK5 by occupying the ATP binding sites of CDK5, exerting an anticancer effect on cervical cancer and breast cancer." (PMID 35006426, 2021). "Tamoxifen can compete for binding with p35 and p25 to inhibit the CDK5 activity in breast cancer." (PMID 35006426, 2021). "Subsequently, mechanism research validated the promoting effect of TGF-β1 secreted by CAFs on the transcription of HOTAIR in breast cancer cells, which will enhance the expression of CDK5 (cyclin dependent kinase 5), thereby facilitating the metastasis of breast cancer cells." (PMID 33520725, 2020). "In addition, phosphorylation of GIV by Cdk5 is to play a role in the migration‐proliferation dichotomy, and in breast cancer, Cdk5 phosphorylation of adducin‐1 is important for epidermal growth factor‐induced cell migration and invasion." (PMID 32352232, 2020). "Cdk5 expression and activity has been linked with the development and progression of cancer; however, its expression in breast cancer has not been fully described." (PMID 32352232, 2020). "Indeed, knockdown of Cdk5 was found to impair actin remodeling in breast cancer cells and melanoma cells; however, the molecular mechanisms remain poorly understood." (PMID 31548578, 2019). "Lately, Pao-Hsuan Huang and colleagues reported CDK5 could directly target p21, and overexpression of CDK5 triggered the degradation of p21 and promoted several cancer cells (breast cancer, prostate cancer, lung cancer) growth." (PMID 31311512, 2019).
breast carcinoma (continued). "In breast cancer, upregulated expression of CDK5 was related to higher grading (grading III)." (PMID 26860827, 2016). "In breast cancer, CDK5 was essential for the motility of cancer cell." (PMID 26860827, 2016). "CDK5 may be a potential link between WNT4 and p70-S6K, as CDK5 has been linked to non-canonical Wnt signaling as well as mitochondrial function in breast cancer cells." (PMID 33053661, 2020). "In addition to breast cancer, CDK5 mRNA expression is important in other tumour types; in blood cancers, low CDK5 mRNA expression has been shown to be associated with adverse survival (n = 53) and high CDK5 expression has been associated with shorter overall survival in lung cancer." (PMID 32352232, 2020). "Here, Ren and colleagues demonstrate that the TGFβ1/HOTAIR axis, by targeting CDK5 signaling, promotes the metastatic capacity of breast cancer cells, thus suggesting that its targeting may be considered a novel strategy for the treatment of breast cancer." (PMID 30927908, 2019). "In addition, depletion of Cdk5 was found to impair actin remodeling in breast cancer cells." (PMID 31548578, 2019). "Moreover, CDK5 was proven to be essential for TGF-β1-induced EMT in breast cancer progression." (PMID 29325547, 2018). "A striking example is observed in breast cancer brain metastasis, where astrocytes—a key component of the brain TME—upregulate Cdk5 in metastatic cancer cells." (PMID 41369365, 2025). "For instance, Cdk5-mediated phosphorylation of FAK at Ser732, an event required for neuronal migration, is repurposed in breast cancer to drive invasion." (PMID 41369365, 2025). "Dinaciclib, a drug that targets CDK1, CDK2, CDK5, and CDK9, has demonstrated efficacy in the treatment of breast cancer by reducing the expression of stem cell markers and decreasing cancer cell viability." (PMID 40004024, 2025). "In breast cancer, CDK1, CDK5, and CDK20 are overexpressed, while CDK2 and CDK6 are decreased, with high expression correlating with poor prognosis." (PMID 39567714, 2024). "Accordingly, in breast cancer, prostate cancer, lung cancer, colorectal cancer, melanoma, pituitary adenoma, leukemia, hepatocellular carcinoma (HCC), gliomas and MTC, both CDK5 and p35 levels are increased." (PMID 37993880, 2023). "The authors observed that stimulation of in vitro cultured breast cancer cells with transforming growth factor β1 (TGF-β1) upregulated the expression of CDK5 and of p35 leading to an increased CDK5 activity." (PMID 31910742, 2020). "High expression of CDK5 mRNA has been shown to be associated with adverse metastasis‐free survival in a large study of 456 patients; patient clinicopathological variables and breast cancer‐specific survival were not described, so a direct comparison with the current study cannot be made." (PMID 32352232, 2020). "In this study, we identified ADD1 as a novel substrate of Cdk5 and demonstrated that ADD1 phosphorylation at T724 by Cdk5 is important for EGF-induced cell migration and invasion in MDA-MB-231 breast cancer cells." (PMID 31548578, 2019). "Finally, cyclin-dependent kinase 5 (Cdk5) is a proline-directed serine/threonine kinase that localize in the inner mitochondrial membrane and is important for the development of several cancers, and especially in breast cancer, where it correlates with poor prognosis." (PMID 30011966, 2018). "High expression of CDK5 or p35 had been demonstrated to be involved in the cancer cell motility and metastasis potential via EMT, such as in breast cancer, lung cancer, and head and neck squamous cell carcinoma." (PMID 27406233, 2016). "In breast cancer CDK5 participates in TGF-β1-induced epithelial-mesenchymal transition and TGF-β1 upregulates CDK5 and p35 expression." (PMID 25625291, 2015). "We demonstrate that an antibody that selectively detects a validated CDK5 phosphorylation site on the substrate CRMP2 robustly stains NSCLC, B-cell lymphoma and to a lesser extent breast carcinoma." (PMID 26555036, 2015).
breast carcinoma (continued). "Interestingly, we observed that LSM4 was closely ranked with other breast cancer biomarkers, such as DPP3, CDK5, and TRIB3." (PMID 34638387, 2021). "In addition, the authors noted significant increases in CDK5 expression with TGFβ treatment, in breast cancer cells, while we did not observe such an effect in NK cells." (PMID 37377891, 2023). "We observed these mPTP opening-induced characteristics in breast cancer cells lacking Cdk5 but Cdk5−/− MEFs also exhibit increased mPTP opening, which is reversed by mPTP desensitizers such as CsA and SFA and show increased [Ca2+]mt level that has been shown to induce mPTP opening." (PMID 32024968, 2020). "Furthermore, they proposed that activated CDK5 phosphorylates FAK at Ser 732 and Tyr397 residues, and this phosphorylation is important for increased expression of α-SMA and for migration and invasion of breast cancer cells." (PMID 31910742, 2020). "However there are also reports that pharmacological (roscovitine) or siRNA inhibition of CDK5 enhances the proliferation of the breast cancer cell lines MCF-7 and MDA-MB321, while application of carboplatin, a chemotherapeutic used in the treatment of breast cancer, induces CDK5 activation." (PMID 26555036, 2015). "Thus, the phosphorylation of CRMP2 in the nuclei of breast epithelium by Cdk5 and GSK-3β may contribute to breast cancer progression." (PMID 24765134, 2014).
prostate carcinoma (37 papers, 2010 to 2025). A carcinoma that arises from epithelial cells of the prostate gland. "A single-nucleotide polymorphism (SNP) in the CDK5 promoter region is linked to aggressive prostate cancer in the African-American population and to lung cancer in the Korean population." (PMID 37993880, 2023). "Clinical evidence has also shown that the level of CDK5 is associated with the progression of prostate cancer." (PMID 31395805, 2019). "It has been reported that protein CDK5 encoded by Isoform1 can phosphorylate AR at its Ser-81 site and therefore activate and stabilize AR to promote prostate cancer cell growth in prostate cancer cell line." (PMID 30367578, 2018). "CDK5 knock-down by siRNA resulted in changes of the microtubule cytoskeleton, loss of cellular polarity and motility in human prostate cancer DU 145 cell line." (PMID 30367578, 2018). "A pre-clinical study showed that digoxin increases intracellular Ca+2 causing changes in the activity of cyclin-dependent kinase Cdk5, cleavage of p35 and formation of p25 leading to prostate cancer cells apoptosis." (PMID 28591151, 2017). "Recently, dysregulation of CDK5 has been linked to malignancy, including cancers of the prostate, pancreas, thyroid, lung, cervix, myeloma, and breast." (PMID 26146988, 2015). "Tilorone was identified as a compound with in vitro synthetical lethality in CDK5-deficient prostate cancer cells." (PMID 24841903, 2014). "Future studies are needed to unravel the mechanism of action of tilorone in CDK5 deficient prostate cancer cells and to test combination therapies with tilorone and a CDK5 inhibitor for its potential use in clinical practice." (PMID 24841903, 2014). "In this study, RA was found to induce cleavage of p35 into p25 and cause Cdk5 overactivation as well as subsequent apoptosis in human prostate cancer cell line DU145." (PMID 23304206, 2012). "We propose that the CDK5–p35 complex might be an outstanding candidate as a diagnostic marker and potential target for prostate cancer treatment in the near future." (PMID 31395805, 2019). "Instead of growth inhibition, high doses of retinoic acid may cause apoptosis of prostate cancer cells though p35 cleavage and Cdk5 overactivation." (PMID 25520935, 2014). "Here, we report that RA might cause apoptosis of androgen-independent prostate cancer cells through novel pathway, in which p35 cleavage and Cdk5 over-activation were involved." (PMID 23304206, 2012). "In conclusion, we report a new mechanism in which RA could cause apoptosis of androgen-independent prostate cancer cells through p35 cleavage and Cdk5 over-activation." (PMID 23304206, 2012). "A crucial target is signal transducer and activator of transcription 3 (STAT3), which Cdk5 directly phosphorylates at Ser727 to enhance its transcriptional activity in prostate cancer and MTC." (PMID 41369365, 2025). "In prostate cancer, Cdk5 additionally targets the androgen receptor (AR), phosphorylating it at multiple sites to increase its stability and activity." (PMID 41369365, 2025). "A recent study revealed CDK5 as a key player that promotes neuroendocrine phenotypes in a prostate cancer patient–derived xenograft (PDX) treatment model upon ADT therapy." (PMID 37993880, 2023). "Overexpression of USF2 was linked to rheumatoid arthritis that is refractory to treatment through upregulation of proinflammatory cytokines, while stabilization of USF2 protein by CDK5-dependent phosphorylation promotes prostate cancer proliferation." (PMID 37515158, 2023). "Talin1 was also shown to be phosphorylated by CDK5 in prostate cancer cells, which activates β1 integrin, promoting invasion." (PMID 37993880, 2023). "CDK5 promotes prostate cancer growth by both activating and stabilizing AR either directly or indirectly." (PMID 37993880, 2023). "CDK5 knockdown or pharmacological inhibition resulted in cytoskeletal remodeling and loss of motility and invasiveness in the highly metastatic AT6.3 prostate cancer cell line." (PMID 37993880, 2023).